EGFR (epidermal growth factor receptor)
Diseases named in the same sentence as EGFR in open-access papers (continued):
Sharing a sentence is not in itself a finding about the gene and the disease.
adenocarcinoma (continued). "EGFR-TKI has been shown to induce a partial response in SCLC patients carrying EGFR-activating mutations, which are described as SCLC combined adenocarcinoma components." (PMID 24396447, 2014). "Currently, we can offer these treatments routinely to patients with EGFR-mutated and ALK-rearranged NSCLC, the vast majority of whom have adenocarcinoma histology." (PMID 25157335, 2014). "This meta-analysis revealed that the EML4-ALK fusion gene is highly correlated with a never/light smoking history, female and the pathologic type of adenocarcinoma, and is largely mutually exclusive of EGFR." (PMID 25360721, 2014). "Histopathological specimens, which were obtained bronchoscopically from the mass in the right lung, revealed an adenocarcinoma with an exon 19 deletion in the epidermal growth factor receptor (EGFR) gene." (PMID 25187837, 2014). "The main purpose of the study was to assess EGFR expression by immunohistochemistry and correlate with the morphologic subtypes according to the new adenocarcinoma classification." (PMID 25763322, 2014). "We were able to show significant differences concerning EGFR FISH patterns in adenocarcinoma subtypes (p = 0.029)." (PMID 25227424, 2014). "The prevalence of EGFR and ALK mutations in GGO nodules in this study was compared to previous reports of adenocarcinoma of all types." (PMID 24885886, 2014). "Further conclusions on selecting anti-EGFR antibody therapies need larger numbers of case studies and molecular genetic analysis in the intestinal-type adenocarcinoma arising from MCTs." (PMID 25297496, 2014). "The present meta-analysis of 17 studies, which included 4511 cases, revealed that the EML4-ALK fusion gene is highly correlated with a never/light smoking history, female and the pathologic type of adenocarcinoma, and is largely mutually exclusive of EGFR." (PMID 25360721, 2014). "A number of adenocarcinoma-specific gene alterations are known, including EGFR, KRAS and BRAF, and these affect the gene products of the MAP kinase and PI3/AKT signaling pathways." (PMID 25364428, 2014). "IRF8 protein expression was frequently silenced in males, smokers, patients with non-adenocarcinoma or with wild-type EGFR, or in an advanced stage." (PMID 25120651, 2014). "In summary, our multicohort analyses of genomic and transcriptional alterations demonstrate both differences and strong similarities between the EGFR and KRAS mutation defined adenocarcinoma groups." (PMID 24205279, 2013). "The present study was intended to improve our understanding about the EGFR mutation status in NSCLC, especially in non-adenocarcinoma." (PMID 24351833, 2013). "The evaluation of Epidermal Growth Factor Receptor (EGFR) mutations have emerged as the strongest predictor of response to EGFR-tyrosine kinase inhibitors mainly in patients with adenocarcinoma." (PMID 23497146, 2013). "The TBLB specimens were analyzed using a peptide nucleic acid-locked nucleic acid PCR clamp test, and EGFR exon 21 L861Q mutations were detected in both SCLC and adenocarcinoma components." (PMID 24195468, 2013). "EGFR-mutant NSCLC, which often exhibits adenocarcinoma histology, has been found to be associated with a better prognosis compared to EGFR wild-typed NSCLC in most populations, except for a study in Chinese patients." (PMID 27234388, 2013). "Patients with SCLC exhibited a lower degree of peritumoral edema, whereas patients with adenocarcinoma, particularly those treated with EGFR-TKIs, exhibited improved survival rates." (PMID 24649230, 2013). "In adenocarcinoma, the mutational spectrum is dominated by EGFR and KRAS mutations, where the former is an established predictor of response to EGFR inhibitors." (PMID 24205279, 2013). "Lower rates of mutations in the pre-operative cohort to that expected in a Caucasian NSCLC population were observed, with only four EGFR (4%) mutations and nine KRAS (9%) mutations, all occurring in adenocarcinomas as expected." (PMID 23935846, 2013).
adenocarcinoma (continued). "Results of the present study indicated that treatment with EGFR-TKIs leads to an improved prognosis and OS rate in all adenocarcinoma patients." (PMID 24649230, 2013). "Few case reports have described primary EGFR-mutated adenocarcinoma transforming to SCLC and then reverse-transforming to adenocarcinoma." (PMID 24195468, 2013). "Several studies have reported genomic or transcriptional alterations between EGFR-mutated and/or KRAS-mutated tumors and corresponding wild-type adenocarcinomas." (PMID 24205279, 2013). "Patients with adenocarcinoma who were treated with epidermal growth factor receptor (EGFR) tyrosine kinase inhibitors (TKIs) following WBRT, demonstrated a significant improvement in intracranial PFS and OS (P=0.008 and 0.004, respectively)." (PMID 24649230, 2013). "Several of the identified mGISTIC regions harbored known or putative adenocarcinoma driver candidates, such as EGFR, MDM2, KRAS, MYC, TERT, MET, CCND1, NKX2-1/TITF1, CDK4, ERBB2, ID1, RB1, CDKN2A and PTEN." (PMID 24205279, 2013). "Among adenocarcinomas, the prevalence of EGFR positive tumors in each period was 45.5% (N = 51), 38.2% (N = 66) and 41.1% (N = 83), respectively (P = 0.47)." (PMID 23468851, 2013). "Taking the rarity of L861Q mutation among EGFR activating mutations into account, it appears very likely that both the SCLC and adenocarcinoma components shared a common origin." (PMID 24195468, 2013). "The epidermal growth factor receptor tyrosine kinase inhibitors (EGFR-TKIs) have been widely used in the treatment of the advanced non-small cell lung cancer (NSCLC), especially in the adenocarcinoma patients with activating EGFR mutations." (PMID 24113005, 2013). "This conclusion appears consistent with the somewhat mixed inclusion of EGFR-mutated, KRAS-mutated and EGFRwt/KRASwt adenocarcinomas in different reported molecular subtypes of adenocarcinomas." (PMID 24205279, 2013). "Epidermal growth factor receptor (EGFR) gene mutation is one of the most pervasive driver mutations in non-small cell lung cancer (NSCLC), particularly in adenocarcinoma." (PMID 24195468, 2013). "Findings in the present study suggest that patients with adenocarcinoma, particularly those treated with EGFR-TKIs, exhibit improved survival rates." (PMID 24649230, 2013). "There are therapies that target EGFR mutations and ALK fusion genes which are found almost exclusively in adenocarcinomas." (PMID 23190601, 2012). "Several studies, in which East Asia was the focus, have shown that the EGFR mutation rate in NSCLC was about 26% to 38.6%, and the mutation rate increased 32% to 55% in adenocarcinoma." (PMID 22695392, 2012). "First, the data support the importance of lipid metabolic pathway inhibition in adenocarcinoma patients, particularly in those insensitive to anti-EGFR therapy or patients who have developed resistance to such therapy." (PMID 22211244, 2012). "The SOE score for testing patients with EGFR mutant adenocarcinoma who have developed EGFR TKI resistance is therefore ‘high’." (PMID 22363766, 2012). "The three most frequently altered genes in a subgroup of smokers with adenocarcinoma were EGFR (22.0%), STK11 (19.0%), and KRAS (12.0%)." (PMID 22768234, 2012). "Our study showed that the EGFR mutation rate was 50.0% in advanced cases of NSCLC and 51.8% in cases of adenocarcinoma." (PMID 22695392, 2012). "First results indicating the possibility of such a mechanism came from adenocarcinoma cells in which oxidative stress led to a co-localization of ceramides and activated EGFR and SFK." (PMID 23228165, 2012). "In patients with adenocarcinomas, the predominant histology of EGFR-mutant tumors, pleural metastases are a frequent finding." (PMID 22091430, 2011). "EML4-ALK fusion occurs in a mutually exclusive fashion with EGFR or KRAS mutations and, almost exclusively, in adenocarcinomas." (PMID 21785682, 2011). "Multivariate analysis of progression-free survival of the 37 adenocarcinoma patients treated with EGFR TKIs." (PMID 21858063, 2011).
adenocarcinoma (continued). "Here we also performed a limited comparison of the ability of COLD-PCR to detect EGFR and KRAS mutations in 25 EBUS-derived adenocarcinoma cytological aspirates with that of standard-PCR." (PMID 21949883, 2011). "For 45 adenocarcinomas having SNP array data, direct sequencing detected a high frequency of KRAS (n = 21, 47%) or EGFR (n = 14, 31%) mutations." (PMID 19826477, 2009). "al. identified frequent EGFR protein over expression (62%) in NSCLCs of squamous cell and adenocarcinoma subtypes." (PMID 19238210, 2009). "For instance, the transmembrane receptor EGFR (epidermal growth factor receptor) is expressed at high levels in adenocarcinomas." (PMID 19812696, 2009). "On the other hand, 62 patients (51 men/11 women; median age: 66 years; adenocarcinoma: 43 patients) were judged to have wild-type EGFR." (PMID 17106442, 2006). "High POU6F1 expression was significantly associated with younger age (p = 0.027), female sex (p = 0.041), non-smoking status (p = 0.002), adenocarcinoma histology (p = 0.021), and the presence of EGFR mutations (p = 0.038)." (PMID 42193061, 2026). "We identified four EGFR exon 18 mutations and six EGFR exon 19 deletions in 82 adenocarcinoma patients initially reported as having no genetic mutations." (PMID 39947926, 2025). "Higher levels of CA-125 and CA-199 may be more effective than CEA in predicting poor PFS in patients with stage IV adenocarcinoma, with CA-125 demonstrating particular effectiveness in those who received EGFR TKIs." (PMID 40361443, 2025). "Adenocarcinoma, the most common subtype, is often peripheral, commonly found in non-smokers, and expresses markers like TTF-1, Napsin A, and CK7, with potential mutations in EGFR and ALK that can be targeted with specific therapies." (PMID 40827171, 2025). "In patients diagnosed with adenocarcinoma or unspecified NSCLC without activating mutations in the EGFR gene, the status of the ALK and ROS1 genes should be evaluated to detect rearrangements that occur in 3–5% and 1% of patients, respectively." (PMID 40076671, 2025). "Also, a higher proportion of women have epidermal growth factor receptor (EGFR) mutations in NSCLC and an increased incidence of adenocarcinoma with lepidic features." (PMID 40486071, 2025). "Consequently, the gene silencing and/or drug‐dependent inhibition of the MR kinases AKT1, CDK1&2, ERBB2 and the downstream kinase EGFR markedly reduced cell viability in a large panel of human adenocarcinoma cell lines." (PMID 39995112, 2025). "Multiple studies have demonstrated significant associations between EGFR mutations and female sex, non-smoking status, and specific adenocarcinoma histologic subtypes." (PMID 40708937, 2025). "In addition to its activity on the EGFR-mutant receptor in adenocarcinoma, EGFR TKIs have been found to modulate the immune microenvironment and enhance cytotoxic T-cell killing." (PMID 41256964, 2025). "A 39-year-old woman diagnosed with Stage IV adenocarcinoma of the left lung, negative for EGFR, ALK, and ROS-1, but with an ERBB2 mutation, experienced neurological symptoms leading to a diagnosis of brain metastasis in 2019." (PMID 41180730, 2025). "Estos hallazgos coinciden con la evidencia existente sobre el valor de algunos marcadores concretos para predecir algunos perfiles histológicos: CEA y CA 15–3 para el adenocarcinoma, donde las mutaciones en EGFR son más prevalentes, y CYFRA 21–1 y SCC para el carcinoma de células escamosas." (PMID 40977824, 2025). "Mutations in the EGFR gene are identified in approximately 10–16% of NSCLCs, with a higher frequency among patients with adenocarcinoma and non-smoking patients." (PMID 40591555, 2025). "For example, in adenocarcinoma (ADC) patients, lepidic-predominant lesions may have negative or low PD-L1 expression but are more likely to harbor EGFR mutations." (PMID 40624192, 2025). "In EGFR-mutant adenocarcinoma, the survival benefit from ICIs was limited." (PMID 41008908, 2025).
adenocarcinoma (continued). "The patient was then diagnosed with non‐small cell right lung cancer cT1bN1M0 (stage IIB), adenocarcinoma with lepidic component, EGFR (+) exon 18 (G719C belongs G719Xsubstitutions)/non‐small left lung cancer cT1bN0M0 (stage IA2)/Papillary Thyroid cancer cT1N0M0." (PMID 40855618, 2025). "The ALK kinase mutation mainly affects patients with adenocarcinoma (especially young men), and, as in the case of EGFR mutations, a negative association with smoking has been demonstrated." (PMID 40076671, 2025). "Importantly, actionable KRAS and EGFR alterations make up a significant portion of overall actionable alterations in advanced NSCLC (adenocarcinoma), together accounting for 44% in Western populations and up to 60% in Asian populations." (PMID 40282516, 2025). "EGFR amplifications were observed in 19% of adenocarcinoma cases, while less pronounced gains of this locus were already detectable in early stages, suggesting that these alterations may precede more severe amplification events." (PMID 40149421, 2025). "EGFR-TKIs were reported to be less effective in EGFR-mutated LSCC than in adenocarcinoma (ADC), although no large-scale prospective trial has been conducted." (PMID 40351934, 2025). "For example, EGFR mutations are found in nearly 50% of Asian non-smoking adenocarcinoma patients, compared to 10–15% in Western populations, suggesting a gene–environment interaction that modulates risk." (PMID 41303058, 2025). "Clinically, EGFR ex20ins mutations are often enriched in patients with adenocarcinoma histology and never-smoking status and are associated with poorer outcomes compared with tumors harboring classical sensitizing EGFR mutations." (PMID 41585239, 2025). "This risk factor has been linked to mutations in EGFR, adenocarcinoma histology, non-smokers, and better prognosis." (PMID 40430005, 2025). "However, prolonged survival has been reported in patients with symptomatic bone marrow metastasis from EGFR‐, ERBB2‐ mutated or ALK fusion—positive adenocarcinoma treated with tyrosine kinase inhibitors." (PMID 41314797, 2025). "We also found that the non-mucous adenocarcinomas with extracellular mucus had a lower EGFR mutation rate." (PMID 40182027, 2025). "Previous research has shown that females, adenocarcinoma patients and non-smokers are more likely to have EGFR mutations, a finding consistent with our results." (PMID 40242240, 2025). "A 39-year-old woman was diagnosed with Stage IV adenocarcinoma of the left lung, which tested negative for EGFR, ALK, and ROS-1 mutations, while showing a 2% expression of PD-L1 and an ERBB2 mutation." (PMID 41180730, 2025). "EGFR mutations were more frequently observed in adenocarcinoma than SCC (27.7% vs. 13.0%), this difference was not statistically significant (p = 0.080)." (PMID 41327362, 2025). "EGFR mutations—particularly exon 19 deletions and L858R substitutions—were more frequent in adenocarcinomas and non-smokers and were associated with improved survival, especially in HPV-negative cases." (PMID 41327362, 2025). "The population of women with NSCLC studied was characterized by non-smoking, adenocarcinoma histological type dominance, and a high percentage of EGFR mutations." (PMID 41425682, 2025). "EGFR mutations are common in Asian individuals, women, those with no history of smoking, and patients with adenocarcinoma." (PMID 40620186, 2025). "All tumors containing an EGFR mutation and 91.1% of KRAS mutated cases were adenocarcinomas." (PMID 40591555, 2025). "EGFR mutation rate is higher in adenocarcinoma and non-smoking patients, and the prognosis is better in patients with EGFR mutations." (PMID 39634906, 2024). "Some common clinical characteristics seen in patients with EGFR mutations are non-smoking status, adenocarcinoma histology, female sex, and East Asian ethnicity." (PMID 38539465, 2024). "Of 71 patients with adenocarcinoma in our study, EGFR mutation status was available for 59 patients, all without EGFR mutation." (PMID 39148905, 2024).
adenocarcinoma (continued). "Consequently, this study provides a potent non-invasive tool for predicting EGFR gene mutation status and HER2 overexpression in adenocarcinoma brain metastases, thereby greatly enhancing patient prognosis." (PMID 38773634, 2024). "Mutations in the epidermal growth factor receptor (EGFR) tyrosine kinase are observed in approximately 15% of NSCLC adenocarcinomas in the United States and occur more frequently in nonsmokers." (PMID 38473302, 2024). "This study developed a T1-CE signature that could serve as a non-invasive adjunctive tool to determine the presence of EGFR mutations and HER2 + status in adenocarcinoma, aiding in the direction of treatment plans." (PMID 38773634, 2024). "The majority (61.4%) had adenocarcinoma, and 34.3% harbored a mutant EGFR-TK." (PMID 39429333, 2024). "Previous research has revealed that EGFR mutations, particularly 19‐Del and 21‐L858R, are more prominent in women, individuals with adenocarcinoma, nonsmokers, and the East Asian population." (PMID 38659399, 2024). "Magnetic resonance (MR)-based radiomics features of brain metastases are utilised to predict epidermal growth factor receptor (EGFR) mutation and human epidermal growth factor receptor 2 (HER2) overexpression in adenocarcinoma, with the aim to identify the most predictive MR sequence." (PMID 38773634, 2024). "EGFR mutations are detected more frequently in women, non-smokers, adenocarcinoma, and Asian populations." (PMID 39205175, 2024). "One plausible explanation for gender’s exclusion could be the inclusion of adenocarcinoma as a predictor, as other histological types in our sample less frequently underwent EGFR testing." (PMID 39650554, 2024). "EGFR mutations are prevalent in NSCLC, particularly in adenocarcinoma." (PMID 39130636, 2024). "Since KRAS and EGFR mutational status were examined in only 29.5% (13/44) and 9.1% (4/44) of the patients with adenocarcinoma enrolled in this study, respectively, they were not included as study variables in logistic regression." (PMID 38504315, 2024). "The most frequent mutations in NSCLC include exon 19 deletion (45–50% of all EGFR mutated cases) and exon 21 substitution (L858R) (35–45% of all EGFR mutated cases) that are commonly found in non-smoking women from East Asia with adenocarcinoma." (PMID 39513892, 2024). "Besides, we revealed a higher prevalence of TLS-high cases in (i) the female compared to the male category, (ii) the adenocarcinoma compared to the squamous cell subtype, and (iii) EGFR mutant compared to EGFR wild-type samples." (PMID 39376565, 2024). "In NSCLC, particularly in adenocarcinoma subtypes common among non-smokers or light smokers, mutations in the epidermal growth factor receptor (EGFR) are a primary oncogenic driver." (PMID 39286635, 2024). "The adenocarcinoma showed epidermal growth factor receptor (EGFR) mutation, no anaplastic lymphoma kinase (ALK) expression, and less than 1% expression of programmed death ligand 1 (PD-L1) by immunohistochemistry." (PMID 38336778, 2024). "Most patients were in Stage IV (78.3%), had adenocarcinoma (89.1%) and were EGFR mutation-negative (76.1%) and ALK fusion-negative (89.1%)." (PMID 38594880, 2024). "The EGFR mutation rate is higher in adenocarcinoma and non-smoking patients, and the prognosis is better in patients with EGFR mutations." (PMID 39634906, 2024).